CRP (C-reactive protein)
Diseases named in the same sentence as CRP in open-access papers (continued):
Sharing a sentence is not in itself a finding about the gene and the disease.
ankylosing spondylitis (continued). "CRP elevation is infrequently found in nr-axSpA patients, but is elevated in less than 30% of radiographic axSpA/ankylosing spondylitis (AS) patients with active disease." (PMID 33990221, 2021). "Clinical remission criteria selected were AS Disease Activity Score Inactive Disease (ASDAS-ID) and Bath Ankylosing Spondylitis Disease Activity Index (BASDAI) < 2 with normal C-reactive protein (CRP) levels (BASDAI-CRP)." (PMID 34575390, 2021). "For example, STIM1 polymorphisms have been shown to associate with the inflammatory index (erythrocyte sedimentation rate and C-reactive protein) in ankylosing spondylitis patients." (PMID 33348924, 2020). "Laboratory assessment was based on inflammation parameters; clinical assessment was performed with the Ankylosing Spondylitis Disease Activity Score- (ASDAS-) CRP and Bath Ankylosing Spondylitis Disease Activity Index (BASDAI)." (PMID 32317863, 2020). "Adjusted hazard ratios (HRs) for ankylosing spondylitis according to hs-CRP concentrations at baseline, using different models and sensitivity analyses." (PMID 30768617, 2019). "Incidence of ankylosing spondylitis (AS) according to hs-CRP concentration, with stratification by sex and age." (PMID 30768617, 2019). "High levels of CRP at baseline also predicted improved adalimumab persistence at 24 months in our hands, a finding that has also been observed previously in ankylosing spondylitis as well as PsA patients." (PMID 31920675, 2019). "They found that anti-14-3-3η (eta) was significantly increased in sera of AS patients and correlated with SIJ inflammation, C-reactive protein (CRP), baseline modified stoke ankylosing spondylitis spine score (mSASSS), and change in mSASSS in AS patients." (PMID 30723468, 2019). "The Ankylosing Spondylitis Disease Activity Score (ASDAS) includes the C reactive protein (CRP) or the erythrocyte sedimentation rate (ESR) or both to discriminate between high and low disease activity." (PMID 31253169, 2019). "We also illustrated the application of the proposed method to the Prospective Study of Outcomes in Ankylosing spondylitis (AS) (PSOAS) data to address the issues of censored or missing C-reactive protein (CRP) level at early visits for a group of patients." (PMID 29325529, 2018). "In patients with ankylosing spondylitis, methylation of SOCS-1 significantly associated with severity of patient's spondylopathy, sacroiliitis and acute phase reactant CRP." (PMID 28915645, 2017). "CRP levels do correlate at the group level with clinical disease activity, decrease upon effective treatment and are included in the ankylosing spondylitis disease activity score (ASDAS)." (PMID 25135077, 2014). "The high MMP cluster was associated with increased C-reactive protein, the BASDAI and the Bath ankylosing spondylitis functional index." (PMID 22640827, 2012). "In this example, although it seemed natural to use the PRS of ankylosing spondylitis (the disease of interest) or CRP (the trial outcome) as the risk score, they do not explain the HTE." (PMID 41282753, 2025). "The demographical data, erythrocyte sedimentation rate (ESR), and c-reactive protein (CRP) levels of the patients were determined, and the Bath Ankylosing Spondylitis Disease Activity Index (BASDAI) assessment for AS patients and DAS28 (disease activity score) for RA patients were assessed." (PMID 39734351, 2024). "At 3 years with: Taking NSAIDs between visits [OR= 5.42; CI 95% (1.40–20.97)] (p-value:0,014) and a high average ankylosing spondylitis disease activity score with C-reactive protein (ASDAS CRP) on the day of the visit [OR= 2.84; CI 95% (1.43–5.63)] (p-value:0,003)." (PMID 39886292, 2024). "Outcomes included disease activity (Ankylosing Spondylitis Disease Activity Score-C reactive protein (ASDAS-CRP), joint and enthesitis count, CRP), patient-reported outcomes for function (Health Assessment Questionnaire for axSpA, HAQ-AS) and quality of life, and treatment use over 6 years." (PMID 35091462, 2022).
ankylosing spondylitis (continued). "Ankylosing Spondylitis Disease Activity Score (ASDAS) is a disease activity scale that is relatively more objective than BASDAI as it involves either C-reactive protein (CRP) or erythrocyte sedimentation rate (ESR), and is widely used in estimating disease activity for AS." (PMID 35685583, 2022). "To further evaluate our hypothesis, we asked whether persistent elevation of CRP could be found in radiographic axSpA (or ankylosing spondylitis [AS]) patients in our cohort." (PMID 33990221, 2021). "In addition, clinical assessment indicators including ankylosing spondylitis disease activity score, bath ankylosing spondylitis disease activity index, bath ankylosing spondylitis functional index, c-reactive protein were also analyzed." (PMID 33382842, 2020). "For example, C-reactive protein (CRP) is one of the primary biomarkers known to reflect the degree of inflammation in the body and it has been widely used for studies of Ankylosing spondylitis (AS) to monitor disease activity, assess response to treatment and predict radiographic progression." (PMID 29325529, 2018). "Younger age, shorter symptom duration or elevated C-reactive protein (CRP) values were found to be predictive of a Bath ankylosing spondylitis disease activity index (BASDAI)-50 response or an assessment of the SpondyloArthritis International Society (ASAS)-40 response to TNF-blockers." (PMID 24476416, 2014). "Additionally, while the HLA-B27 marker associated with ankylosing spondylitis did not demonstrate abnormal expression in the monkey, the expression of C-reactive protein (CRP) in the proteome showed a notable increase (4.43-fold)." (PMID 39877611, 2025). "Interestingly, we note that the HTE of secukinumab on ankylosing spondylitis was not explained by the genetic predisposition to ankylosing spondylitis itself or by the trial outcome CRP." (PMID 41282753, 2025). "Clinical assessment included Bath Ankylosing Spondylitis Disease Activity Index (BASDAI), erythrocyte sedimentation rate (ESR), and C-reactive protein (CRP)." (PMID 41989727, 2026). "Maastricht Ankylosing Spondylitis Enthesitis Score (MASES) and disease activity in means of Bath Ankylosing Spondylitis Disease Activity Index (BASDAI) and Ankylosing Spondylitis Disease Activity Score with C-reactive protein (ASDAS-CRP) were also recorded." (PMID 41553409, 2026). "Disease activity measures included Bath Ankylosing Spondylitis Disease Activity Index (BASDAI), Ankylosing Spondylitis Disease Activity Score (ASDAS), and C-reactive protein (CRP) levels." (PMID 40648848, 2025). "The interaction between BMD PRS and treatment on ASDAS-CRP remained significant after conditioning on the PRS of ankylosing spondylitis (estimated PRSxT coefficient = 0.477, P = 0.0007) and the PRS of CRP (estimated PRSxT coefficient = 0.903, P = 5.2e-5)." (PMID 41282753, 2025). "HRV was found to be lower in AS patients, and their values were negatively correlated with the blood level of C-reactive protein (CRP) and the score of Bath ankylosing spondylitis disease activity index (BASDAI)." (PMID 38318588, 2024). "IFX, infliximab; IV, intravenously; ASAS, ASsessment in AS; AS, ankylosing spondylitis; BASDAI, Bath AS Disease Activity Index; BASFI, Bath AS Functional Index; GAP, global assessment of pain; CRP, C-reactive protein; ESR, erythrocyte sedimentation rate." (PMID 38952586, 2024). "The outcomes assessed were ≥20% improvement in the Assessment of Spondyloarthritis International Society Criteria (ASAS20), Bath Ankylosing Spondylitis Functional Index (BASFI), and C-reactive protein (CRP) at weeks 12-16." (PMID 38571822, 2024). "Unetscore: Inflammatory score from U-net model; ESR, erythrocyte sediment rate; CRP, C-reactive protein; BASDAI, Bath Ankylosing Spondylitis Disease Activity Index; ASDAS, Ankylosing Spondylitis Disease Activity Score." (PMID 36935744, 2023).
ankylosing spondylitis (continued). "The Bath Ankylosing Spondylitis Disease Activity Index (BASDAI) and the Ankylosing Spondylitis Disease Activity Score (ASDAS)-CRP were used for evaluating disease activity." (PMID 35685583, 2022). "HO-1 expression was positively related to erythrocyte sedimentation rate (ESR), C-reactive protein (CRP) and Ankylosing Spondylitis Disease Activity Score (ASDAS)." (PMID 35784335, 2022). "LncRNA-AK001085 level was also negatively correlated with erythrocyte sedimentation rate (ESR), C-reactive protein (CRP), Ankylosing Spondylitis Disease Activity Score (ASDAS), and Bath Ankylosing Spondylitis Disease Activity Index (BASDI)." (PMID 35222376, 2022). "Similar results were obtained regarding markers of inflammation (CRP and ESR) or disease activity (Bath Ankylosing Spondylitis Disease Activity Score, Ankylosing Spondylitis Disease Activity Score and Bath Ankylosing Spondylitis Functional Index)." (PMID 33849644, 2021). "Bath ankylosing spondylitis disease activity index (BASDAI), Bath ankylosing spondylitis functional index (BASFI), C-reactive protein (CRP) and erythrocyte sedimentation rate (ESR) were recorded after admission to the hospital." (PMID 34724925, 2021). "Ankylosing Spondylitis Disease Activity (ASDAS) includes patient-reported individual and a global activity score and either c-reactive protein (CRP) or erythrocyte sedimentations rate (ESR)." (PMID 32367294, 2020). "This systematic review and NMA compared the efficacy of all current and investigational treatment options for ankylosing spondylitis by assessing ASAS20 response, change from baseline in BASFI, and change from baseline in CRP." (PMID 32107666, 2020). "Disease activity was measured using the Bath Ankylosing Spondylitis disease activity index (BASDAI), and the Ankylosing Spondylitis disease activity score (ASDAS), using the C-reactive protein." (PMID 31269678, 2019). "Patients had active disease according to Bath ankylosing spondylitis disease activity index (BASDAI) and ankylosing spondylitis disease activity score (ASDAS) and had higher CRP levels compared with HC (p = 0.008)." (PMID 30057583, 2018). "Demographic data, disease activity scores using Bath Ankylosing Spondylitis Disease Activity Index (BASDAI), medical history, C-reactive protein (CRP), erythrocytes sedimentation rate (ESR), and complete blood count (CBC) were measured." (PMID 30174952, 2018). "Other endpoints assessed through week 52 included improvements in ASAS40, ASAS 5/6, Bath Ankylosing Spondylitis Disease Activity Index, and ASAS partial remission responses, as well as the change from baseline in high-sensitivity C-reactive protein levels." (PMID 29273067, 2017). "Ankylosing spondylitis subjects showed higher HOMA-IR, ESR, TG and CRP levels, compared with control group (P<0.01)." (PMID 27383120, 2016). "Only recently was a new ankylosing spondylitis disease activity score (ASDAS) developed, which incorporates the CRP value in addition to PRO measures, or - alternatively - the erythrocyte sedimentation rate." (PMID 24476416, 2014). "In SpA patients, serum VEGF levels correlated with disease activity indices as defined by the Bath Ankylosing Spondylitis Disease Activity Index (BASDAI), erythrocyte sedimentation rate, or C-reactive protein (CRP)." (PMID 19203382, 2009). "Erythrocyte sedimentation rate (ESR) and C-reactive protein (CRP) were measured in patients and volunteers, and Bath Ankylosing Spondylitis Disease Activity Index (BASDAI) and Bath Ankylosing Spondylitis Functional Index (BASFI) scores were also calculated and recorded in the patient group." (PMID 40963322, 2025). "At week 12, those achieving ASDAS-CRP (Ankylosing Spondylitis Disease Activity Score - C-reactive protein) major improvement (MI; Δ≥2.0) continued 10 mg; non-responders escalated to 15 mg." (PMID 41209988, 2025).
ankylosing spondylitis (continued). "Erythrocyte sedimentation rate, C-reactive protein (CRP), Bath Ankylosing Spondylitis Disease Activity Index, Ankylosing Spondylitis Disease Activity Score CRP, visual analog scale, and Disease Activity Score-28 CRP markers at months 0, 3, and 12 of secukinumab treatment were analyzed." (PMID 40806803, 2025). "Significant negative correlations were found between CST and age, ankylosing spondylitis disease activity score–C-reactive protein (ASDAS-CRP), and C-reactive protein." (PMID 40757760, 2025). "ETN, etanercept; IV, intravenously; ASAS, ASsessment in AS; ankylosing spondylitis; CRP, C-reactive protein; ESR, erythrocyte sedimentation rate; BASDAI, Bath AS Disease Activity Index; BASMI, Bath AS Metrology Index; BASFI, Bath AS Functional Index; MRI, magnetic resonance imaging." (PMID 38952586, 2024). "Regardless of elevation of CRP, ASDAS and bath ankylosing spondylitis disease activity index (BASDAI) was associated with presence of carotid plaques." (PMID 37418034, 2023). "VAS, visual analogue scale; ESR, erythrocyte sediment rate; CRP, C-reactive protein; BASDAI, Bath Ankylosing Spondylitis Disease Activity Index; ASDAS, Ankylosing Spondylitis Disease Activity Score; DMARD: Disease-modifying anti-rheumatic drug; MTX, sulfasalazine; SSZ, Sulfasalazine." (PMID 36935744, 2023). "In clinical practice, it is hard to judge the level of disease activity in some patients with ankylosing spondylitis (AS) who have low traditional acute phase reactant values such as erythrocyte sedimentation rate (ESR) and C-reactive protein (CRP) but have considerable pain and inflammation." (PMID 35685583, 2022). "The major variables of result comprised erythrocyte sedimentation rate (ESR), C-reactive protein (CRP), Spinal Pain Visual Analog Score (SP-VAS), Bath Ankylosing Spondylitis Functional Index (BASFI), and Bath Ankylosing Spondylitis Disease Activity Index (BASDAI)." (PMID 35281463, 2022). "Correlation analysis suggested that the expression levels of hsa_circ_0000652 were statistically correlated with the Ankylosing Spondylitis Disease Activity Score (ASDASCRP), Bath Ankylosing Spondylitis Disease Activity Index (BASDAI), and level of C-reactive protein (p < 0.001)." (PMID 34977002, 2021). "Additionally, the FCs of the left precuneus and left middle temporal gyrus of AS patients were closely related to Bath Ankylosing Spondylitis Disease Activity Index (BASDAI) scores, erythrocyte sedimentation rate (ESR), and C-reactive protein (CRP)." (PMID 33329370, 2020). "In addition, ESR and serum CRP are two common laboratory measures of disease activity, and the BASDAI or Ankylosing Spondylitis Disease Activity Score (ASDAS) are frequently used to determine disease severity." (PMID 31777200, 2020). "AS patients showed significant correlation between CRP with clinical parameters such as pain, morning stiffness, enthesitis-related local discomfort, BASDAI, BASFI (Bath ankylosing spondylitis functional index), and BASMI (Bath ankylosing spondylitis metrology index)." (PMID 30944880, 2019). "Additionally, M-MDSC levels correlated positively with the clinical index of AS, including the Bath ankylosing spondylitis disease activity index (BASDAI) score, erythrocyte sedimentation rate (ESR) and C-reactive protein (CRP) levels." (PMID 30075733, 2018). "Demographic and clinical data such as gender, age, onset age, disease duration, erythrocyte sedimentation rate (ESR), highly sensitive C-reactive protein (hs-CRP) and the Bath Ankylosing Spondylitis Disease Activity Index (BASDAI) were collected from the SAPHO syndrome patients." (PMID 30517110, 2018). "For example, in the Prospective Study of Outcomes in Ankylosing Spondylitis (PSOAS), CRP data not only were censored due to limits of detection but also were incompletely collected at early study visits because blood sample collection was not a part of the original study design." (PMID 29325529, 2018).
ankylosing spondylitis (continued). "At the onset of colitis, there were a long-term disease duration from 10 to 25 years (17.5 ± 6.5), high Bath Ankylosing Spondylitis Disease Activity Index (BASDAI) 7.5 to 8.8 (8.2 ± 0.5), and elevated levels of ESR (35 to 80, 55.0 ± 18.7 mm/hr) and CRP (18.8 to 60.2, 34.4 ± 18.0 mg/L)." (PMID 29030592, 2017). "Demographic and disease characteristics at baseline showed significantly more active disease (Bath Ankylosing Spondylitis Disease Activity Index, total back pain, nocturnal back pain, patient global, ASDAS, CRP) (P <0.0001 for all variables) in patients who received TNFα inhibitor therapy." (PMID 24755322, 2014). "Disease activity was assessed using Bath ankylosing spondylitis disease activity index (BASDAI), Bath ankylosing spondylitis functional index (BASFI), and Bath ankylosing spondylitis metrological index (BASMI) scores and C-reactive protein (CRP) and erythrocyte sedimentation rate (ESR) levels." (PMID 24803936, 2014). "Failure to respond is defined as a Bath Ankylosing Spondylitis Disease Activity Index (BASDAI) of at least 4.0 and raised inflammatory markers (erythrocyte sedimentation rate (ESR) >25 mm/hour and/or C-reactive protein (CRP) >10.0 mg/L)." (PMID 20107564, 2009). "Notably, lncRNA-NEF expression exhibited a significant correlation with Ankylosing spondylitis disease activity score (ASDAS), Bath Ankylosing Spondylitis Disease Activity Index (BASDAI), erythrocyte sedimentation rate (ESR), and C-reactive protein (CRP) levels (p < 0.05)." (PMID 38590778, 2024). "However, in the Outcome Assessments in Ankylosing Spondylitis International Study cohort, elevated CRP at baseline in patients with AS did not emerge as an independent predictor for the development of new syndesmophytes and/or bridges in the spine at 4 years." (PMID 30768617, 2019). "Continuous measures of diseases activity, such as Bath Ankylosing Spondylitis Disease Activity Index (BASDAI), ASDAS and CRP as well as symptom duration were not correlated with increased frequencies of CD27-CD38lowCD21low B-cells." (PMID 34168654, 2021).